COIL (coilin)
Description:
Component of nuclear coiled bodies, also known as Cajal bodies or CBs, which are involved in the modification and assembly of nucleoplasmic snRNPs.
Synonyms: CLN80; p80-coilin
Tractability: PROTAC: UniProt records ubiquitination sites on it; ubiquitination databases record sites on it; its protein half-life has been measured.
Gene: Protein-coding gene on chromosome 17 (56,938,199 to 56,961,050, reverse strand). Ensembl gene ENSG00000121058.
Subcellular location: Nucleus; Nucleus, Cajal body
Subcellular location (Human Protein Atlas): Nuclear bodies; Nucleoli fibrillar center; Nucleoplasm
Gene Ontology:
Molecular function: identical protein binding; protein binding
Biological process: spliceosomal snRNP assembly
Cellular component: Cajal body; fibrillar center; membrane; nuclear body; nucleolus; nucleoplasm; nucleus
Genetic constraint (gnomAD): Loss-of-function variants: 27 observed, 49.33 expected, observed/expected ratio (o/e) 0.55, 90% interval 0.4 to 0.75. The upper end of that interval is the gene's LOEUF score, 0.75, which puts it in group 3 of 6, group 1 being the genes least tolerant of losing a copy. Missense variants: 617 observed, 650.49 expected, observed/expected ratio (o/e) 0.95, 90% interval 0.89 to 1.01. Synonymous variants: 217 observed, 247.97 expected, observed/expected ratio (o/e) 0.88, 90% interval 0.78 to 0.98.
Homologues: Orthologues: chimpanzee COIL (99% identical), rabbit COIL (77% identical), dog COIL (75% identical), pig COIL (66% identical), mouse Coil (66% identical), guinea pig COIL (65% identical), rat Coil (65% identical), tropical clawed frog coil (32% identical), zebrafish coil (32% identical).
Diseases named in the same sentence as COIL in open-access papers:
COIL is named in the same sentence as 25 diseases in open-access papers, as found by Europe PMC text mining. Sharing a sentence is not in itself a finding about the gene and the disease. The quoted sentences say what the papers report.
viral infection (4 papers, 2020 to 2025). "CBs coordinate maturation and processing of small nuclear RNA (snRNA), small nucleolar RNA (snoRNA) and histone mRNAs, while its hallmark protein coilin (p80-coilin) is particularly altered during viral infections." (PMID 32585969, 2020). "Our results suggest that PARP1 could act as a key molecular actuator in the regulatory network which integrates coilin activities as a stress sensor for virus infection and SA-mediated antivirus defence." (PMID 37376582, 2023). "Taking into account that CBs/coilin may trigger responses to virus infection via interaction with PARP and modulation of its activity, it would be conceivable to select a wide range of DNA and RNA viruses to address their ability to multiply in parp, parg or nudix knockout or knockdown plants." (PMID 36680280, 2023). "In this review, we focus on Class VI TRIM proteins, including TRIM24, TRIM28, and TRIM33, highlighting the distinct functional attributes of their RING, B-BOX1, B-BOX2, COILED COIL, PHD, and BRD domains in viral infection." (PMID 40421416, 2025).
acute lymphoblastic leukemia (2 papers, 2018 to 2022). Leukemia with an acute onset, characterized by the presence of lymphoblasts in the bone marrow and the peripheral blood. "The exact profile and associated functions of coilin, as well as p27, in children’s acute lymphoblastic leukemia (ALL) is obscure." (PMID 30065619, 2018). "Coilin has been suggested to have a crucial function in CB-related RNA processing, which is known to affect drug resistance in acute lymphoblastic leukemia (ALL)." (PMID 35151311, 2022).
cervical carcinoma (2 papers, 2020 to 2021). A carcinoma arising from either the exocervical squamous epithelium or the endocervical glandular epithelium. "Here, we compared the numbers of CBs by observing coilin foci in a normal human lung cell line (BEAS-2B) against two lung cancer cell lines (A549 and H1299) and a cervical cancer cell line (HeLa)." (PMID 32764415, 2020). "The increased sample size enabled identification of SMGs previously unreported in cervical carcinoma including NBPF10 (8%), RANBP2 (6%), MSN (6%), KRT8 (6%), POTEC (6%), ZC3H11A (4%), BMS1 (4%), GPX1 (3%), OTOP1 (3%), DNAH12 (2%), COIL (2%), TBC1D26 (2%), SPRED3 (2%), FAM115A (2%), and ARIH1 (1%)." (PMID 34620846, 2021).
leukemia (2 papers, 2018 to 2025). A malignant (clonal) hematologic disorder, involving hematopoietic stem cells and characterized by the presence of primitive or atypical myeloid or lymphoid cells in the bone marrow and the blood. "To make sure that the changes in CB and coilin were indeed the consequence of DNA damages, we also treated the cells with other agents used in leukemia therapies of AraC or VCR." (PMID 30065619, 2018). "We prepared a pair of lentivirus vector carrying either a control or a coilin shRNA expressing cassette to evaluate the knockdown effect of coilin in leukemia cells." (PMID 30065619, 2018). "With the rapid progress in the development and application of high-content clinical microscopic equipment, the examination of coilin or perhaps other marker proteins of CBs could be used to form a big data digital source to allow cumulative research for leukemia treatments." (PMID 30065619, 2018).
neuroblastoma (2 papers, 2009 to 2013). Neuroblastoma (NB) is the most common solid, extracranial childhood tumor. "In this study, we have investigated the relationship between CBs and gems and the methylation of endogenous coilin in the human neuroblastoma cell line SH-SY5Y as it undergoes differentiation and neurite outgrowth." (PMID 19735367, 2009). "During embryonic development, coilin and SMN localize to different nuclear body structures, but transcription of neuroblastoma SH-SY5Y cells with retinoic-acid increases their colocalization." (PMID 24358231, 2013).
spinal muscular atrophy (2 papers, 2005 to 2023). A motor neuron disease that affect the muscles, and characterized by muscle weakness and atrophy resulting from progressive degeneration and irreversible loss of the anterior horn cells in the spinal cord (i.e., lower motor neurons) and the brain stem nuclei. "The marker protein for CBs, coilin, may play a role in snRNP biogenesis given that it can interact with snRNPs and SMN, the protein mutated in Spinal Muscular Atrophy." (PMID 16008839, 2005). "Besides p80 coilin, Cajal bodies contain small nuclear ribonucleoproteins (snRNPs) and the survival of motor neuron proteins (SMN), proteins related to spinal muscular atrophy." (PMID 38283335, 2023).
colon cancer (1 paper, 2022). "Our findings expand our understanding about functional natural substrates of UHMK1 and further demonstrated the importance of coilin phosphorylation in colon cancers, especially in context of drug sensitivity and resistance." (PMID 35151311, 2022). "We observed a significant decrease in CB counts in HCT-8 colon cancer cells following 5-FU treatment, as shown by immunofluorescence of coilin and Survival of motor neuron (SMN), another CB marker protein." (PMID 35151311, 2022). "In conclusion, we identified that coilin is phosphorylated at serine residues by UHMK1 in colon cancer cells, and this phosphorylation subsequently regulates CB assembly and contributes to colon cancer cell resistance to 5-FU." (PMID 35151311, 2022).
E. coli infection (1 paper, 2022). "In addition, further studies are required to explore the mechanisms of coilin translocation caused by E. coli infection." (PMID 34980188, 2022). "We observed coilin translocation from the nucleus to the cytoplasm upon meningitic E. coli infection." (PMID 34980188, 2022). "In this study, we characterized an abundantly expressed lncRNA, lncC11orf54-1, which was degraded by translocated coilin to produce mgU2-19 and mgU2-30 in hBMECs during E. coli infection." (PMID 34980188, 2022). "Our data confirmed that E. coli infection in hBMECs induced the translocation of coilin, which led to the processing of lncC11orf54-1 into mgU2-30." (PMID 34980188, 2022).
primary biliary cirrhosis (1 paper, 2013). "Anti-p80 coilin has been detected in SS or SSc, especially when associated with primary biliary cirrhosis." (PMID 23556533, 2013).
prostate carcinoma (1 paper, 2024). A carcinoma that arises from epithelial cells of the prostate gland. "We find heterologous responses to the platinum-based drugs that are associated with prostate cancer cell types with different AR status, and we identify Coilin and TDP-43 as prominent platinum-responsive nuclear proteins." (PMID 38218884, 2024). "In response to platinum drug treatments, prostate cancer cells exhibited highly heterologous changes in distribution of Coilin-immunopositivity in relation to nucleoli with frequent localization of Coilin close or within the nucleoli." (PMID 38218884, 2024). "Our findings provide insight into the heterologous responses of prostate cancer cells to different platinum drug treatments and indicate Coilin and TDP-43 as stress mediators in the varied outcomes." (PMID 38218884, 2024). "This co-localization is retained in carboplatin treated LNCaP cells, while occasional co-localization of FUS and Coilin is detected upon other platinum drug treatments in the prostate cancer cell lines tested." (PMID 38218884, 2024). "We also find that CB-associated, stress-responsive RNA binding proteins FUS and TDP-43 control Coilin and CB biology in prostate cancer cells and, further, that TDP-43 is associated with stress-responsive CBs in prostate cancer cells." (PMID 38218884, 2024). "Taken together, these results show that a stress response of CBs follows exposure of prostate cancer cells to platinum drugs, and this is quantitatively reflected in Coilin immunostaining patterns." (PMID 38218884, 2024). "Since Coilin was observed to localize to chromatin void areas upon platinum drug-induced stress and the number of Coilin spots seemed to change, we tested whether Coilin translocates to nucleoli in prostate cancer cells in response to platinum drugs." (PMID 38218884, 2024). "Since CBs underwent clear alterations upon platinum drug treatment in prostate cancer cells as measured via Coilin and SMN1 localization, we quantified this phenomenon using Coilin as a marker." (PMID 38218884, 2024). "Co-immunostaining with Coilin revealed that FUS is nucleoplasmic and exhibits clear localization in CBs only in LNCaP cells of the prostate cancer cell lines tested." (PMID 38218884, 2024). "Since CBs underwent drastic changes upon platinum drug exposure as measured by translocation of two significant CB proteins Coilin and SMN1, we then asked what other proteins might be involved in CB homeostasis in prostate cancer cells." (PMID 38218884, 2024). "The role of TDP-43 and co-regulation of TDP-43 and Coilin and/or CBs warrants further investigation in terms of cancer drug responses especially since TDP-43 levels decrease in advanced prostate cancer and this may affect the nuclear responses of prostate cancer cells to cytotoxic drugs." (PMID 38218884, 2024).
cancer (11 papers, 2005 to 2025). A tumor composed of atypical neoplastic, often pleomorphic cells that invade other tissues. "We screened through The Cancer Genome Atlas (TCGA) database searching for cancer patients with coilin mutation at residue 121 or 145 to further investigate the relationships between coilin and cancer." (PMID 32764415, 2020). "Here, we performed clinical bioinformatic analysis and found that coilin mutation at residue 121 or 145 is rare in patients of various cancer types." (PMID 32764415, 2020). "Additionally, clinical bioinformatic analysis indicated that coilin expression levels could be a risk factor for cancer, depending on the cancer types and races." (PMID 32764415, 2020). "Furthermore, clinical bioinformatic analysis indicates that coilin expression may potentially be a risk factor for cancer, depending on the cancer types and races." (PMID 32764415, 2020). "Like SMN and WRAP53, the expression of coilin is also increased in transformed cells compared to primary cells, further indicating that coilin is part of the upregulated RNP biogenesis machinery present in cancer cells." (PMID 24659245, 2014). "Curiously, U7 snRNPs are localized to CBs in human cancer cells and HLBs and CBs share other common components, including coilin." (PMID 22558428, 2012). "Moreover, even though many studies have shown that CBs exist in a range of cancer cell lines, the relationships between CB, coilin expression, and cancer have remained largely elusive." (PMID 32764415, 2020). "When focused only on the African datasets, survivals of four cancer types (bladder carcinoma, cervical squamous cell carcinoma, sarcoma, and uterine corpus endometrial carcinoma) appeared to be positively or negatively correlated with the COIL expressions." (PMID 32764415, 2020). "The data indicated that these coilin mutations were extremely rare in cancer patients, suggesting that coilin SNP variants are likely not cancer risk factors (data not shown)." (PMID 32764415, 2020). "Additionally, clinical bioinformatic analysis was also performed in order to evaluate the possible relationships between coilin and cancers." (PMID 32764415, 2020). "We propose that AIDA-1c expression in neuronal and cancer cell lines may facilitate snRNP biogenesis by modulating the interaction between coilin and snRNPs." (PMID 15862129, 2005). "However, subsequent analysis showed that the coilin expression levels correlated with patient survival in some cancer types, and that population might also be a factor." (PMID 32764415, 2020). "However, since our previous data indicated that coilin SNP variants could give rise to different levels of protein and gene expressions, we then sought to determine the roles of coilin expression in cancer survival." (PMID 32764415, 2020). "In the Asian population, survivals of three cancer types (head-neck squamous cell carcinoma, liver hepatocellular carcinoma, and stomach adenocarcinoma) were significantly correlated with COIL expressions, and stomach adenocarcinoma was only found to be related to COIL expression in this population." (PMID 32764415, 2020). "In most cases, the significant correlations between COIL expression and survival of a particular cancer type, for it be a positive or negative correlation, are consistent across different populations." (PMID 32764415, 2020). "In human cancer cells, however, the U7 snRNP accumulates in CBs and not HLBs, but CBs and HLBs share other common components, such as coilin." (PMID 24659245, 2014). "The connections between coilin and cancer have not been systematically assessed." (PMID 32764415, 2020). "Finally, the work presented here underscores why cancer cells invariably contain CBs: this subnuclear domain not only increases the efficiency of snRNP biogenesis but also may enhance scaRNP formation via coilin interactions with both proteins and scaRNAs." (PMID 24659245, 2014).
infection (7 papers, 2014 to 2023). The state of being infected such as from the introduction of a foreign agent such as serum, vaccine, antigenic substance or organism. "The only antibody that produced any co-localization with p80-coilin was raised against the L4-33K protein, which was detected in a fraction of microfoci in the late phase of infection." (PMID 37795984, 2023). "Overall, these results suggest that the CB protein p80-coilin forms a stable complex with L4-22K and facilitates Ad mRNA transport throughout all phases of infection, pointing to a new role for the CB in Ad infection." (PMID 37795984, 2023). "The 16K-induced nucleolar relocalisation of coilin occurring upon TRV infection results in an increase in the nucleolar retention of PARP1, thereby preventing it trafficking from the nucleolus to CBs for PAR cleavage and recycling." (PMID 37376582, 2023). "In agreement with this idea, depletion of Cajal bodies through knock-down of coilin was previously found to promote the infection by the geminivirus Tomato golden mosaic virus." (PMID 33064077, 2020). "For example, centromeres damaged by infection with herpes simplex virus accumulate coilin and coilin associates with specific RNA and DNA sequences in the cell." (PMID 24659245, 2014). "In contrast with the previous results, coilin-silenced plants show milder symptoms upon infection by Potato virus Y (PVY) (Potyviridae, Potyvirus) and Turnip vein clearing virus (Virgaviridae, Tobamovirus), pointing to a positive role of coilin in the viral cycle." (PMID 32102236, 2020). "Interestingly, coilin silencing had an effect on the infection by all tested viruses, including RNA and DNA viruses, although a general rule is not easy to infer." (PMID 32102236, 2020). "Toward this objective, we analysed the progression of infections established by wildtype (wt) and VSR-defective PLPV in plants with fibrillarin or coilin content diminished through RNAi approaches." (PMID 35893605, 2022). "Coilin/CBs may be recruited by some viruses for enhancement of their replication, but interestingly these cell components may in some cases, such as with tobacco rattle virus (TRV;), act to suppress infection." (PMID 37376582, 2023). "Despite the fact that PLPV p37 has the ability to interact with and relocalize coilin to the nucleolus, similar to that described for TRV 16K, coilin reduction had no obvious consequences for PLPV infection." (PMID 35893605, 2022).
tumor (1 paper, 2017). "Interestingly, in some tumor cells, the functional properties of coilin are associated with both CBs and nucleoli." (PMID 28337219, 2017). "Thus, nucleolar proteins, including coilin that also appears in nucleoli of tumor cells, appear to be involved in the DNA repair machinery, which is, for example, also activated in Purkinje cells during neurodegeneration, characterized by the disintegration of nucleoli and CBs." (PMID 28337219, 2017).
COIL also shares sentences with these, for which no sentence is quoted: alveolitis (1 paper); amyotrophic lateral sclerosis (1); Ataxia (1); atypical hemolytic-uremic syndrome (1); bronchiectasis (1); fibrosis (1); heart disease (1); lung carcinoma (1); microangiopathic hemolytic anemia (1); preeclampsia (1); renal failure (1); Thrombocytopenia (1).